CKMT1B (creatine kinase, mitochondrial 1B)
Description:
Reversibly catalyzes the transfer of phosphate between ATP and various phosphogens (e.g. creatine phosphate). Creatine kinase isoenzymes play a central role in energy transduction in tissues with large, fluctuating energy demands, such as skeletal muscle, heart, brain and spermatozoa.
Synonyms: CKMT; UMTCK; CKMT1
Target class: Enzyme; Transferase
Gene: Protein-coding gene on chromosome 15 (43,593,054 to 43,604,901, forward strand). Ensembl gene ENSG00000237289.
Subcellular location: Mitochondrion inner membrane
Pathways (Reactome):
Metabolism: Creatine metabolism
Gene Ontology:
Molecular function: protein binding; creatine kinase activity; catalytic activity; kinase activity; phosphotransferase activity, nitrogenous group as acceptor; transferase activity, transferring phosphorus-containing groups
Biological process: phosphocreatine biosynthetic process
Cellular component: mitochondrion; mitochondrial inner membrane
Genetic constraint (gnomAD): Loss-of-function variants: 7 observed, 16.44 expected, observed/expected ratio (o/e) 0.43, 90% interval 0.24 to 0.8. The synonymous counts are far from expectation, so gnomAD's model fits this gene poorly and the ratio says little. Missense variants: 136 observed, 190.48 expected, observed/expected ratio (o/e) 0.71, 90% interval 0.62 to 0.82. Synonymous variants: 40 observed, 67.34 expected, observed/expected ratio (o/e) 0.59, 90% interval 0.46 to 0.77.
Homologues: Orthologues: rabbit CKMT1B (98% identical), mouse Ckmt1 (97% identical), rat Ckmt1 (97% identical), tropical clawed frog ckmt1b (84% identical), zebrafish ckmt1 (81% identical), Drosophila melanogaster Argk1 (38% identical), Caenorhabditis elegans F46H5.3 (37% identical), Caenorhabditis elegans F32B5.1 (36% identical), Caenorhabditis elegans W10C8.5 (36% identical), Drosophila melanogaster Argk2 (35% identical), Caenorhabditis elegans argk-1 (34% identical), Drosophila melanogaster CG4546 (34% identical), and 2 more. Paralogues in human: CKMT1A (100% identical), CKMT2 (79% identical), CKB (61% identical), CKM (59% identical).
Diseases named in the same sentence as CKMT1B in open-access papers:
CKMT1B is named in the same sentence as 22 diseases in open-access papers, as found by Europe PMC text mining. Sharing a sentence is not in itself a finding about the gene and the disease. The quoted sentences say what the papers report.
Obesity (4 papers, 2020 to 2025). Accumulation of substantial excess body fat. "Nine variants in the protein-coding sequence of CKMT1B were detected in the mutation screen of 192 children and adolescents with severe obesity and 192 lean control individuals." (PMID 37101650, 2023). "Furthermore, we detected that the variant rs149544188 located in CKMT1B was nominally less frequently transmitted by a heterozygous parent to the child with obesity than expected (transmission rate of 36%, pChi-square = 0.16)." (PMID 37101650, 2023). "With this, the infrequent alleles of the variants rs76220640 (p.Pro112 =) and rs146047573 (p.Tyr269Cys) located in CKB, the CKMT1B variant rs9571's allele (p.Lys352 =) as well as the allele of the GATM-located variant rs747005297 (p.His292Arg) were nominally associated with obesity." (PMID 37101650, 2023). "The presence of infrequent non-synonymous variants in CKB and CKMT1B (rs146047573, rs758572075, rs1230355611, and rs149544188) was confirmed in independent study groups comprising 781 families with severe obesity, 320 children and adolescents with severe obesity, and 253 healthy lean controls." (PMID 37101650, 2023). "The CDSs of CKB, CKMT1B, and GATM were subsequently screened for variants in 192 children and adolescents with severe obesity as well as 192 healthy-lean controls." (PMID 37101650, 2023). "Transgenic mice depleted of CKB, CKMT1B, and GATM showed impaired creatine biosynthesis capacity affecting the murine body weight and resulting in a susceptibility to obesity." (PMID 37101650, 2023). "Moreover, the single nucleotide polymorphisms in CKB and CKMT1B were associated with BMI54, indicating that CKB and CKMT1 are involved in the pathogenesis of obesity in vivo." (PMID 39107469, 2024). "Additionally, VAT CKMT1B expression was higher in patients with obesity in comparison to individuals with a BMI lower than 30 kg/m2." (PMID 37101650, 2023). "The genes CKMT1A and CKMT1B, which encode key mitochondrial creatine kinases and reported to be involved in UCP1-independent thermogenesis, were among those being significantly less expressed in FTO obesity-risk samples." (PMID 32316277, 2020). "For CKB, CKMT1B and GATM, subsequent analyses revealed gene expression differences between VAT and SAT in 1,448 adipose tissue donors with obesity." (PMID 37101650, 2023). "Deviations between participants with and without obesity in the VAT were exclusively observed for CKMT1B (padj. < 0.001)." (PMID 37101650, 2023). "CKMT1B’s expression was even higher in individuals with obesity than non-obese individuals." (PMID 37101650, 2023). "Based on these data, we analyzed correlations between CKB, CKMT1B, and GATM expression levels and specific metabolic and anthropometric parameters in both VAT and SAT of participants with and without obesity." (PMID 37101650, 2023). "By analyzing RNA-seq data of VAT and SAT of 1,479 individuals (1,448 with obesity and 31 non-obese) of the Leipzig Obesity Biobank, we detected that all three genes of interest (CKB, CKMT1B and GATM) showed positive correlations with each other in visceral fat." (PMID 37101650, 2023). "Considering the inverse correlations of CKB with CKMT1B and GATM in visceral and subcutaneous adipose tissue, we subsequently performed between-subject comparisons of non-obese participants and individuals with obesity from the LOBB for all three genes studied." (PMID 37101650, 2023).
glioma (3 papers, 2021 to 2025). A benign or malignant brain and spinal cord tumor that arises from glial cells (astrocytes, oligodendrocytes, ependymal cells). "Meanwhile, Low expression of CKMT1B is associated with a poor prognosis and immune infiltration in glioma." (PMID 33465115, 2021). "CKMT1B is a prognostic biomarker with potential applications and associated with immune infiltration in Lower-grade glioma." (PMID 33465115, 2021). "CKMT1B, implicated in immune infiltration and glioma prognosis, was also downregulated." (PMID 40559957, 2025). "A recent study found potential for CKMT1B expression as a prognostic biomarker in glioma; similarly, alterations in CHL1 expression have been associated with development and metastasis of many types of cancer." (PMID 39132489, 2024). "In the present study, we investigated the potential role of CKMT1B in LGG and analyzed the expression of CKMT1B in a large cohort of human glioma patients for the first time." (PMID 33465115, 2021). "The mechanism of CKMT1B in glioma cells is still unclear, but many studies have proved that CKMT1B was closely related to the occurrence and development of tumors." (PMID 33465115, 2021).
breast carcinoma (2 papers, 2020 to 2021). "Notably, the overexpression of CKMT1B predicted a poor prognosis in breast cancer and hepatocellular carcinoma." (PMID 33465115, 2021).
cardiomyopathy (1 paper, 2021). A disease of the heart muscle or myocardium proper. "CKMT1B has been reported as a major target of oxidative induced molecular damage in ischemic, cardiomyopathy and neurodegenerative diseases." (PMID 33465115, 2021).
hearing loss (1 paper, 2022). "Thus, most of the homozygous STRC deletions associated hearing loss cases carried a 2 copy number loss of the whole CKMT1B-STRC-CATSPER2 gene region." (PMID 35022556, 2022). "Among 108 cases with a 2 copy loss of the whole CKMT1B-STRC-CATSPER2 gene region, 52 cases were male and the prevalence of DIS in patients with hearing loss associated with a 2 copy number loss of the STRC gene was estimated to be 37.1% (52/140)." (PMID 35022556, 2022).
hepatocellular carcinoma (1 paper, 2021). A malignant tumor that arises from hepatocytes. "High expression of CKMT1B indicates highly malignant potential in hepatocellular carcinoma." (PMID 33465115, 2021).
hypopharynx cancer (1 paper, 2024). A primary or metastatic malignant neoplasm that affects the hypopharynx. "Additionally, the burden of LoF in CKMT1B was associated with hypopharynx cancer (OR=1.03, p =3.9 × 10−26 ), vertiginous syndromes (OR=1.03, p=3.0× 10−17 ) and salivary glands cancer (OR=1.03; p=3.2× 10−12 )." (PMID 39132489, 2024).
Infertility (1 paper, 2024). "This demonstrates that the infertility phenotype was caused by the homozygous deletion of CATSPER2 alone rather than by deletion of STRC and/or CKMT1B." (PMID 38165034, 2024). "Moreover, the infertility phenotype of patients with homozygous deletion of CATSPER2 (patient C5), homozygous deletion of CATSPER2 combined with heterozygous deletion of STRC and CKMT1B (patients C6–C8), or homozygous deletion of CATSPER2, STRC, and CKMT1B (patients C1–C4) was indistinguishable." (PMID 38165034, 2024).
prostate carcinoma (1 paper, 2021). A carcinoma that arises from epithelial cells of the prostate gland. "The K-M survival curve analyses of 128 patients with prostate cancer showed that high-CKMT1B expression slightly reduced the PSA recurrence-free survival rate compared with patients with weak to moderate CKMT1B expression." (PMID 33465115, 2021). "CKMT1B expression was also significantly decreased in poorly differentiated prostate cancer tissues compared with well-differentiated cancer tissues." (PMID 33465115, 2021). "It was reported that CKMT1B (uMtCK) expression was significantly decreased in prostate cancer tissues with higher Gleason scores, a measure of prostate cancer stage, compared with those with lower Gleason scores." (PMID 33465115, 2021).
squamous cell carcinoma (1 paper, 2016). A carcinoma arising from squamous epithelial cells. "One of the identified proteins is CKMT1B, which was also found to be down-regulated in squamous cell carcinomas and in clinical samples." (PMID 27571357, 2016).
cancer (4 papers, 2021 to 2024). A tumor composed of atypical neoplastic, often pleomorphic cells that invade other tissues. "The corresponding heatmap data also showed a positive correlation between CKMT1A and the top 10 correlated genes (excluded CKMT1B) in most cancer types." (PMID 35705641, 2022). "On the one hand, CKMT1B acts as a tumor suppressor by promoting apoptosis of cancer cells." (PMID 33465115, 2021). "The effect of CKMT1B on apoptosis of cancer cells needs further study." (PMID 33465115, 2021). "Moreover, GESA showed that multiple cancer-related and immune-related gene sets were enriched in the low-CKMT1B group in the top 5 of the most significant differences." (PMID 33465115, 2021). "However, it was reported that CKMT1B expression was greatly lower in high Gleason grade carcinoma compared with low grade carcinoma or normal prostate." (PMID 33465115, 2021). "It is suggested that CKMT1B may play an important regulatory role in the progression of cancer." (PMID 33465115, 2021). "However, CKMT1B seems to play a different role in other cancers." (PMID 33465115, 2021). "Additionally, we categorized the 57 cancer cell lines from the Gboxin sensitivity screen into five groups based on their sensitivities, illustrating a positive correlation between the expression of CKMT1A, CKMT1B, and CKB and the cell's sensitivity to Gboxin treatment." (PMID 38896801, 2024).
tumor (3 papers, 2020 to 2023). "Using logistic regression analysis showed that the expression of CKMT1B was associated with tumor grade." (PMID 33465115, 2021). "Our results highlighted that the expression of CKMT1B was associated with tumor grade." (PMID 33465115, 2021). "We used the online website CIBERSORT and TIMER to assess the correlation between CKMT1B and tumor-infiltrating immune cells." (PMID 33465115, 2021). "LGG patients with low expression of CKMT1B were more likely to present a more advanced tumor grade (II vs III, odds ratio = 0.52, p-value<0.001)." (PMID 33465115, 2021). "CKMT1B expression levels in 518 tumor tissues were found to be a vast extent lower than that in 207 normal tissues (P = 5.16E-76)." (PMID 33465115, 2021). "We attempted to relate the CKMT1B expression to a variety of components of immune-infiltrating cells in the tumor microenvironment (TME) of LGG." (PMID 33465115, 2021). "High CKMT1B expression promotes tumor growth by inhibiting apoptosis of tumor cells and down regulating mitochondrial apoptotic pathway proteins." (PMID 33465115, 2021). "Based on the LGG cohort of TCGA, we found that CKMT1B expression was positively correlated with tumor purity (r = 0.097, P<0.05)." (PMID 33465115, 2021). "We observed a significantly lower expression of CKMT1B in the tumor compared with the normal samples by GEPIA." (PMID 33465115, 2021). "Low CKMT1B expression levels may influence mechanisms of tumorigenesis and tumor immunology in LGG progression." (PMID 33465115, 2021). "LGG patients with low expression of CKMT1B were more likely to present a more advanced tumor grade." (PMID 33465115, 2021). "Therefore, we believe that CKMT1B may have a potential influence on tumor immunity." (PMID 33465115, 2021). "Thus, the upregulated expression of CKMT1B may result in more energy for the growing tumor tissue." (PMID 32631357, 2020). "CKMT1B is downregulated in LGG and related to the tumor grade." (PMID 33465115, 2021). "Therefore, in order to further analyze the correlation between CKMT1B and immune cell infiltration in LGG, we operated the online website TIMER which was a web server for comprehensive analysis of tumor-infiltrating immune cells." (PMID 33465115, 2021).
CKMT1B also shares sentences with these, for which no sentence is quoted: Alzheimer disease (1 paper); anorexia nervosa (1); dementia (1); diabetic cardiomyopathy (1); Insulin resistance (1); liver cancer (1); lymph node metastasis (1); male infertility (1); neurodegenerative disease (1); salivary gland cancer (1).